MTMR2 (myotubularin related protein 2)
Description:
Lipid phosphatase that specifically dephosphorylates the D-3 position of phosphatidylinositol 3-phosphate and phosphatidylinositol 3,5-bisphosphate, generating phosphatidylinositol and phosphatidylinositol 5-phosphate. Regulates the level of these phosphoinositides critical for various biological processes including autophagy initiation and autophagosome maturation.
Synonyms: KIAA1073; CMT4B; CMT4B1
Tractability: Small molecule: a structure with a bound ligand is known; it has a binding pocket of medium quality. Antibody: UniProt places it where antibodies can reach, with high confidence. PROTAC: ubiquitination databases record sites on it; its protein half-life has been measured.
Gene: Protein-coding gene on chromosome 11 (95,821,766 to 95,925,315, reverse strand). Ensembl gene ENSG00000087053.
Subcellular location: Cytoplasm; Early endosome membrane; Cytoplasm, perinuclear region; Cell projection, axon; Endosome membrane
Subcellular location (Human Protein Atlas): Vesicles
Pathways (Reactome):
Metabolism: Synthesis of PIPs at the ER membrane; Synthesis of PIPs at the early endosome membrane; Synthesis of PIPs at the late endosome membrane; Synthesis of PIPs at the plasma membrane
Gene Ontology:
Molecular function: phosphatidylinositol-3,5-bisphosphate 3-phosphatase activity; phosphatidylinositol-3-phosphate phosphatase activity; protein binding; identical protein binding; phosphatidylinositol phosphate phosphatase activity
Biological process: phosphatidylinositol dephosphorylation; regulation of phosphatidylinositol dephosphorylation; dendritic spine maintenance; negative regulation of endocytosis; negative regulation of excitatory postsynaptic potential; negative regulation of receptor catabolic process; negative regulation of receptor internalization; phosphatidylinositol biosynthetic process; positive regulation of early endosome to late endosome transport
Cellular component: cytoplasm; cytosol; early endosome membrane; extracellular exosome; nucleus; axon; dendrite; dendritic spine; endosome membrane; membrane; postsynaptic density; synaptic membrane; synaptic vesicle; perinuclear region of cytoplasm; vacuolar membrane
Genetic constraint (gnomAD): Loss-of-function variants: 47 observed, 66.56 expected, observed/expected ratio (o/e) 0.71, 90% interval 0.56 to 0.9. The upper end of that interval is the gene's LOEUF score, 0.9, which puts it in group 3 of 6, group 1 being the genes least tolerant of losing a copy. Missense variants: 575 observed, 691.81 expected, observed/expected ratio (o/e) 0.83, 90% interval 0.77 to 0.89. Synonymous variants: 213 observed, 240.41 expected, observed/expected ratio (o/e) 0.89, 90% interval 0.79 to 0.99.
Gene-disease validity (ClinGen):
ClinGen rates the evidence that MTMR2 causes each of these diseases.
demyelinating hereditary motor and sensory neuropathy (autosomal recessive): Definitive.
Homologues: Orthologues: chimpanzee MTMR2 (100% identical), macaque MTMR2 (99% identical), guinea pig MTMR2 (98% identical), pig MTMR2 (98% identical), rabbit MTMR2 (98% identical), mouse Mtmr2 (97% identical), dog MTMR2 (95% identical), rat Mtmr2 (87% identical), zebrafish mtmr2 (72% identical), tropical clawed frog mtmr2 (71% identical), Drosophila melanogaster mtm (55% identical), Caenorhabditis elegans mtm-1 (41% identical), and 10 more. Paralogues in human: MTMR1 (69% identical), MTM1 (61% identical), MTMR3 (36% identical), MTMR4 (34% identical), MTMR6 (33% identical), MTMR8 (33% identical), MTMR7 (33% identical), SBF1 (30% identical), SBF2 (29% identical), MTMR9 (28% identical), MTMR10 (24% identical), MTMR12 (22% identical), and 1 more.